CDC42 (cell division cycle 42)
Diseases named in the same sentence as CDC42 in open-access papers (continued):
Sharing a sentence is not in itself a finding about the gene and the disease.
endometriosis (continued). "However, both studies describe variants in loci on chromosome 1 encoding for CDC42 and WNT4 as risk factors for uterine fibroids and endometriosis and similarly report variants in loci on chromosome 6 encoding for SYNE1 and ESR1 as risk factors for both conditions." (PMID 36304022, 2021). "The strongest burden statistic was on chromosome 1p36 (the region encompassing ZBTB40, WNT4 and CDC42), with two types of ovarian cancer (clear cell carcinoma and high-grade serous carcinoma, while epidemiologically, endometriosis does not constitute a risk factor for this last type of cancer)." (PMID 34298916, 2021). "Only rs12037376 (CDC42/WNT4), rs71575922 (SYNE1/ESR1), and rs77294520 (GREB1) associate with leiomyoma after correction for the number of tests (P < 0.05/19 = 2.6 × 10−3), with all three variants showing the same direction of effect for endometriosis and leiomyoma (logistic regression)." (PMID 30194396, 2018). "In hESC cells co-cultured with gestational epithelial endometriosis organoids, SFRP1, CDC42, RAC1, and WASF3 were upregulated, while PTK2B was downregulated, reflecting the miRNA cargo of ENDO-GEST-derived EVs." (PMID 42282918, 2026). "At 1p36.12, there is an important locus involved in endometriosis encompassing LINC00339, CDC42 and WNT4 in a LD block of ~130 kb." (PMID 34298916, 2021).
viral infection (19 papers, 2005 to 2025). "Most notably, we observed that inhibitors of the Rho GTPase family of cytoskeletal regulators—including RhoA, Cdc42, and Rho-associated kinase signaling pathways—significantly reduced viral infection." (PMID 28114951, 2017). "Together, these data indicate that CDC42 primarily promotes HBV entry via NTCP receptor for effective viral infection." (PMID 40954218, 2025). "The increased viral infection phenotype upon RNAi of act-5, wsp-1, wve-1, and cdc-42 was also confirmed by measuring viral load with qRT-PCR." (PMID 37131627, 2023). "After HEV capsid proteins were expressed in the cytoplasm for viral assemble, they directly interact with CDC42 following viral infection." (PMID 34790187, 2021). "Some previous studies have documented that CDC42 signaling pathways can be involved in different stages of viral infection, including viral entry, intracellular trafficking, egress, and cell-to-cell transmission." (PMID 34790187, 2021). "For other flaviviruses, it was shown that the expression of the dominant-negative GTPase mutants of Rac1 and Cdc42 in HMEC-1 cells specifically inhibits the formation of filopodia induced by DENV-2 leading to a reduction in viral infection and titer." (PMID 34834920, 2021). "Collectively, these results demonstrated for the first time that HEV capsid protein can directly bind to CDC42, and non- and quasi-enveloped HEV use different CDC42 downstream signaling pathways to participate in viral infection." (PMID 34790187, 2021). "Among the inhibitors of small GTPases tested, a Cdc42 inhibitor (ZCL278) reduced viral infection to target cells in MT-2-based co-culture (upper), whereas a Ral inhibitor (BQU57) reduced viral infection in both MT-2- and SLB-1-based co-cultures." (PMID 34843591, 2021). "Members of Rho family small GTPases, such as Rac1 and Cdc42, were described to play roles in virus infection." (PMID 32645930, 2020). "Similar studies performed with HIV demonstrated similar results when Cdc42 was inhibited with secramine A, indicating the potential role of Cdc42 in viral infections." (PMID 27014223, 2016). "Therefore, understanding the explicit function of CDC42 in different viral infections remains an area of active research." (PMID 40954218, 2025). "Previous studies have shown that crosstalk pathways led by downstream CDC42 play a decisive role in membrane remodeling during viral infection in the Rap1b-triggered cascade signaling pathway, which significantly differs between enveloped and non-enveloped viruses." (PMID 37515145, 2023). "Furthermore, the role of cdc42 in the host response to viral infection has been observed in some aquaculture species." (PMID 34262170, 2021). "Furthermore, inhibition of cdc42, RhoA or Rho-associated protein kinase (ROCK) inhibited viral infection, demonstrating that the appropriate function of Rho family GTPases and their substrates is essential to optimal infection of CD4+ T cells." (PMID 29970186, 2018). "While CDC42 is also implicated in protein transport and secretion, its role in these functions in the context of viral infections has not been fully elucidated." (PMID 40954218, 2025). "Intriguingly, we reveal that CDC42 dependent macropinocytosis is a route for HBV entry, which is equally essential for viral infection as CME." (PMID 40954218, 2025). "Viral infection and PsV colocalization with EEA1 were significantly decreased when cells were treated with Cdc42 siRNA 48 h prior to viral addition." (PMID 35746622, 2022). "After CDC42 overexpression and knockdown assays in LMHOATP1A2 cells were developed, viral infection assays were conducted." (PMID 34790187, 2021). "Cdc42 has been found to be specifically down-regulated in cells latently infected with HIV, suggesting an important role for active Cdc42 in virus infection." (PMID 16080789, 2005). "In addition, after viral infection, the amounts of HEV RNA in the overexpressed-CDC42 group were more than that of the normal group." (PMID 34790187, 2021).
viral infection (continued). "We also show that inhibitors of Rac1 and Cdc42 did not block virus entry, but inhibited overall virus infection." (PMID 32645930, 2020). "It is thus not surprising that CDC42 is involved in viral infection." (PMID 40954218, 2025). "Despite these advances in our understanding of Rho GTPase regulation of cytoskeletal dynamics and viral infection, the precise molecular mechanisms through which RhoA, Cdc42, and ROCK promote viral infection remain unclear and are currently under investigation." (PMID 28114951, 2017).
atherosclerosis (16 papers, 2014 to 2025). A disease characterized by the build-up of fatty material and calcium deposition in the arterial wall resulting in partial or complete occlusion of the arterial lumen. "Moreover, CDC42 signaling is associated with vascular inflammation and the progression of atherosclerosis, which may further contribute to the development of stroke." (PMID 36831829, 2023). "Based on the evidence that CDC42 plays a critical role in regulating atherosclerosis and vascular stiffness, some studies have investigated the abnormal level of CDC42 in patients with cerebrocardiovascular disease." (PMID 38476381, 2024). "For example, one study elucidates that CDC42 regulates chronic inflammation and plaque formation to participate in atherosclerosis." (PMID 38476381, 2024). "For example, one study suggests that CDC42 alleviates atherosclerosis by facilitating reendothelialization of injured arteries." (PMID 37805479, 2023). "CDC42 participates in coronary artery disease by regulating atherosclerosis, systemic inflammation, and blood lipids." (PMID 37805479, 2023). "Cell division control 42 (CDC42) regulates atherosclerosis, blood lipids, and inflammation and thus affects coronary artery disease (CAD), but its utility in drug-coated balloon (DCB)-treated small-vessel CAD (SV-CAD) patients is unclear." (PMID 37805479, 2023). "The direct connection of Cdc42 to VSMC-mediated neointima formation in response to vascular injury or atherosclerosis remains largely unexplored." (PMID 34857846, 2021). "The issue of farnesylation and geranylgeranylation of RhoA, Rac1, and CDc42 in atherosclerosis is important for the therapeutic use of the lipid-lowering agents, statins, in the prevention and reduction of atherosclerosis." (PMID 33379334, 2020). "Cdc42 deletion in endothelial cells significantly attenuates chronic inflammation and plaque formation in atherosclerosis." (PMID 30791562, 2019). "We demonstrated that deletion of CDC42 in endothelial cells prevents chronic inflammation and plaque formation in a murine model of atherosclerosis." (PMID 25057989, 2014). "We also demonstrated that inhibition of Cdc42 signaling in the endothelium decreased vascular inflammation and plaque formation in a mouse model of atherosclerosis." (PMID 25057989, 2014). "CDC42 is reported to regulate blood lipids, atherosclerosis and inflammation." (PMID 40755163, 2025). "Several studies have shown that CDC42 participates in atherosclerosis and vascular stiffness." (PMID 38476381, 2024). "Moreover, Unc5b regulated the migration process through activation of the p-PAK/p-CDC42 signaling pathway, which highlights the potential of this receptor as a therapeutic target for atherosclerosis." (PMID 36670464, 2023). "Importantly, we also found that hypofucosylation of Unc5b regulated by Fut8 enhanced macrophage emigration from intimal lesions and further prevented atherosclerosis through the p-CDC42/p-PAK signaling pathway." (PMID 36670464, 2023). "Among them, CD36, CDC42, JAK2, and STAT3 proteins were closely associated with atherosclerosis and foam cells, and their protein expressions were opposite to those of the ox-LDL group and converged with those of the control group after the sinapine base intervention." (PMID 36903257, 2023). "In addition, CD36, JAK2, STAT3, and CDC42 are essential in reducing lipid accumulation and atherosclerosis in foam cells." (PMID 36903257, 2023). "Reports have shown that RhoA, Rac1, and CDC42 play important roles in atherosclerosis." (PMID 36185329, 2022). "However, Cdc42 activation also plays a role in the formation of atherosclerosis through activation of proinflammatory genes in endothelial cells." (PMID 30791562, 2019). "To test whether endothelial cell Cdc42 deletion also inhibited chronic inflammation in a mouse model of atherosclerosis, we used apolipoprotein E knockout (Apoe KO) mice in which atherosclerotic plaque formation was enhanced by endothelial NF-κB signaling." (PMID 25057989, 2014).
atherosclerosis (continued). "We then further analyzed the influence of Cdc42 on the development of atherosclerosis." (PMID 25057989, 2014). "In addition, Cdc42 activation leads to increased fluid-phase pinocytosis of LDL by macrophages, causing them to absorb excess lipids and turn into foam cells, thereby enhancing in vivo atherosclerosis." (PMID 38068822, 2023). "Therefore, age-related activation of Cdc42 in the liver and macrophages may contribute to dyslipidemia and atherosclerosis." (PMID 38068822, 2023). "Given that atherosclerosis, vascular stiffness, and abnormal differentiation of CD4+T cells are involved in TBAD progression, CDC42 is suspected to serve as a biomarker for TBAD patients in clinical practice." (PMID 38476381, 2024). "Cell division cycle 42 (CDC42) regulates CD4+T-cell differentiation and participates in vascular stiffness and atherosclerosis and is involved in the progression of Stanford type B aortic dissection (TBAD)." (PMID 38476381, 2024). "Aging increases Cdc42 signaling in VSMC, potentially increasing collagen I secretion and leading to vascular fibrosis and atherosclerosis complications." (PMID 38068822, 2023). "Together with CDC42, the role of VAV in modulating LDL-induced actin polymerization and lipid deposition in the arterial wall elucidates the intricate interplay between cellular signaling pathways and lipid metabolism in atherosclerosis." (PMID 39445733, 2025). "Cell division control 42 (CDC42) is a member of the Rho-guanosine triphosphatase family, which plays an important role in the progression of CAD by regulating atherosclerosis, inflammation, vascular recovery, endothelial barrier function, blood lipids, and so on." (PMID 37805479, 2023).
breast tumors (16 papers, 2002 to 2024). "Lastly, the elevated expression of Cdc42 in breast tumor tissues is associated with a lower survival rate in TNBC patients." (PMID 38612766, 2024). "RhoA, RhoB, Rac1/Rac1b, and Cdc42 are overexpressed in breast tumors, with RhoA expression associated with advanced stages of the disease." (PMID 19703301, 2009). "RhoA, Rac1, and Cdc42 are overexpressed in human breast tumors and are all essential for cell migration, indicating that the migratory phenotype we observed in Cx43-shRNA S1 cells is triggered downstream of Rho GTPase signaling." (PMID 30857262, 2019). "The Rho GTPase Cdc42 is overexpressed and hyperactivated in breast tumors compared to normal breast tissue." (PMID 24074261, 2013). "Similar to the ERM protein family (i.e., ezrin and moesin), RhoA, RhoB and Cdc42 immunoreactivity was also observed in the stromal compartment of the breast tumour samples and its blood vessels." (PMID 23420497, 2013). "ST-3 leads to an up-regulation of the small GTPases of the Rho family, RhoC and cdc42, which have an important role in cancer progression, including proliferation, invasion, and metastasis of breast tumours." (PMID 17233884, 2007). "Although Cdc42 is overexpressed and hyperactivated in breast tumors, mutations in Cdc42 have not been found." (PMID 24074261, 2013). "Cdc42 is overexpressed and hyperactivated in human breast tumors." (PMID 24074261, 2013). "Since Rac and Cdc42-regulated MDSCs are known to exert immunosuppressive effects in the TME, we quantitated the MDSCs in SCID mice bearing HER2++ breast tumors following MBQ-167 treatment." (PMID 37397366, 2023). "The initial evidence for Rho GTPases in breast tumor invasion and metastasis in vivo came from studies expressing dominant negative forms of RhoA, RAC1 and Cdc42." (PMID 27902969, 2017). "The data show at the first time that the amount of RhoA-like proteins but not of Rac1 and Cdc42, is related to clinically established prognostic breast tumour markers such as histological grade and proliferation index." (PMID 12237774, 2002). "We conclude from this analysis that (a) high expression levels of a Rac-specific exchange factor does not necessarily correlate with high overall Rac activation, and (b) overall levels of activated Rac and Cdc42 do not necessarily correlate with cell motility in breast tumor cell lines." (PMID 20819206, 2010). "To address the contribution of TTC17/RAP1/CDC42 activation to metastasis in patients with BC, we detected the protein expression of TTC17 and CDC42 in a large cohort of nonmetastatic and metastatic primary breast tumors together with their metastatic lymph node tissues." (PMID 36895029, 2023).
cardiac hypertrophy (16 papers, 2012 to 2025). "These DEP were further linked to Canonical Pathways including Cardiac hypertrophy, Actin cytoskeletal, Cdc42, Cardiac β-adrenergic, and Rac and Rho signaling pathways, as well as Cardiomyocyte differentiation via BMP receptors." (PMID 29695975, 2018). "Furthermore, our results showed that cardiac Cdc42 deficiency ameliorated TAC-induced cardiac hypertrophy and inhibited TAC-induced increases in the expression of hypertrophic genes such as ANP and BNP." (PMID 40610735, 2025). "To further confirm the role of Cdc42 in AngII-induced cardiac hypertrophy in vitro, we isolated adult cardiomyocytes from 8 ~ 10-week-old male Cdc42loxP/loxP and Cdc42CKO mice." (PMID 40610735, 2025). "Our results showed that cardiac Cdc42 deletion significantly suppressed AngII- or TAC-induced cardiac hypertrophy and fibrosis and improved cardiac function in mice." (PMID 40610735, 2025). "In the present study, we investigated the role of Cdc42 in the development of cardiac hypertrophy and fibrosis with TAC- and AngII-induced cardiac remodeling in mice and further explored the relative mechanisms in cardiomyocytes under AngII-treatment in vitro." (PMID 40610735, 2025). "In the present study, we demonstrated that cardiac-specific deletion of Cdc42 significantly alleviated cardiac hypertrophy in vivo and in vitro by blocking the MKK3/6-p38 cascade." (PMID 40610735, 2025). "We also found that Cdc42-mediated MKK3/6-p38 cascade was critical for AngII-induced cardiac hypertrophy in vitro." (PMID 40610735, 2025). "In mouse, microRNA‐133 has been demonstrated to inhibit cardiac hypertrophy through repressing the translation of RhoA, Cdc42, and NELF‐A mRNA." (PMID 33788376, 2021). "MiRNA‐133 is decreased in mouse and human models of cardiac hypertrophy 134 through its regulation of the Ras homolog family member A (RhoA) and cell division control protein 42 homolog (Cdc42)." (PMID 29972883, 2018). "MiR-133 is decreased in mouse and human models of cardiac hypertrophy, and has been shown to inhibit cardiac hypertrophy by targeting RhoA, Cdc42, and Nelf-A/WHSC2." (PMID 22926414, 2012). "The discrepancy in the role of Cdc42 in cardiac hypertrophy and fibrosis might be attributed to the use of different genetic mouse models and the complicated signaling pathways involved in the role of Cdc42 in cardiac hypertrophy." (PMID 40610735, 2025). "However, the role of Cdc42 in pathological cardiac hypertrophy and cardiac remodeling has been reported to be contradictory." (PMID 40610735, 2025). "Therefore, we concluded that Cdc42 plays a key role in cardiac hypertrophy and remodeling by activating the MKK3/6-p38 signaling pathway, and our study provides insight into the mechanism of cardiac hypertrophy and remodeling." (PMID 40610735, 2025). "Taken together, our results demonstrated that the Cdc42-mediated MKK3/6-p38 cascade was critical for cardiac hypertrophy and cardiac fibrosis, and our data emphasized that Cdc42 is a hypertrophic and profibrotic molecule that regulates MKK3/6-p38 signaling in cardiac remodeling." (PMID 40610735, 2025). "Our results are in agreement with those of the study by Birnbaum group, in which Cdc42 expression was greatly enhanced and was found to be responsible for cardiac hypertrophy and fibrosis, and HS-induced cardiac hypertrophy was prevented by the Cdc42-specific inhibitor ML141 in rats." (PMID 40610735, 2025). "Thus, our results suggested that cardiac deletion of the Cdc42 gene significantly alleviated Ang II-induced cardiac hypertrophy by suppressing the activation of the MKK3/6-p38 signaling pathway in the heart." (PMID 40610735, 2025). "Cdc42 has been reported to be involved in cardiac hypertrophy both in vivo and in vitro, however, the role of Cdc42 in cardiac hypertrophy and fibrosis remains unclear or controversial." (PMID 40610735, 2025).
cardiac hypertrophy (continued). "Indeed, while alterations in the Cdc42 and Rac1 signaling of cardiomyocytes affect the development of cardiac hypertrophy and heart failure, these Rho GTPases can have important roles in other cell types of crucial importance in the heart, including cardiofibroblasts and endothelial cells." (PMID 36077014, 2022). "Cardiomyocyte-specific deletion of Cdc42 significantly alleviated transverse aortic constriction (TAC)- and AngII-induced cardiac hypertrophy and fibrosis." (PMID 40610735, 2025). "CDC42-knockout and PAK1-knockout mice develop greater cardiac hypertrophy compared with controls, which demonstrates the contradictory roles of CDC42 and PAK1 in cardiac hypertrophy." (PMID 33824277, 2021). "Constitutively activated Cdc42 enhances cardiomyocyte hypertrophy, and downregulated or inhibited Cdc42 activity attenuates LIF-induced cardiomyocyte elongation or high salt-induced cardiac hypertrophy and fibrosis." (PMID 40610735, 2025). "Notably, the deletion of Cdc42 significantly decreased TAC- and AngII-induced cardiac hypertrophy and remodeling, as indicated by decreases in the LV mass, the HW/BW ratio and fibrosis in the hearts of Cdc42CKO mice." (PMID 40610735, 2025). "Our data showed that Cdc42 deletion significantly reduced the phosphorylation of p38 in AngII-induced cardiac hypertrophy but did not affect the ERK or JNK pathways, which is consistent with the findings of Pellieux." (PMID 40610735, 2025).